CD14 (CD14 molecule)
Diseases named in the same sentence as CD14 in open-access papers (continued):
Sharing a sentence is not in itself a finding about the gene and the disease.
periodontitis (continued). "Therefore, this case-control study was conducted to evaluate the possible influence of immune innate and bone resorption gene polymorphisms, TLR4, CD14, RANKL, and OPG, in periodontitis, in carefully selected patients and controls based on clinical parameters and especially in nonsmokers." (PMID 31281226, 2019). "Interestingly, there is evidence from 2 independent studies that levels of salivary soluble CD14 (sCD14) are elevated in periodontitis; sCD14 mediates the action of LPS and may promote bacterial invasion of host cells in periodontitis." (PMID 24944840, 2014). "Cells from both groups of patients (periodontitis and control) expressed a normal mature phenotype (CD16b + High, CD62L + High, CD15+, and CD14-)." (PMID 39376254, 2024). "Venn diagrams revealed that there were eight shared genes (FAM46C, SLC7A7, LY96, CFI, DDIT4L, CD14, C5AR1, and IGJ) that overlapped between periodontitis and MS which were screened by WGCNA and DEGs." (PMID 38218802, 2024). "Patients with periodontitis have been shown to have elevated numbers of CD14+ monocytes in the GCF —cells that demonstrate high expression of CCR2 and CCR5 compared to CD14− cells in the GCF." (PMID 38139161, 2023). "Another weak relationship in whole blood samples was found between skull types and CD14+ (p = 0.034), CD3+ CD4+ CD8+ (p = 0.034), as well as periodontitis stages three and four and CD3+ CD4+ CD8+ (p = 0.044)." (PMID 36261500, 2022). "The results for CD14 and CD16 are inconsistent with another study, which showed that an increased percentage of CD14+CD16+ monocytes was observed in the blood in chronic periodontitis." (PMID 35055157, 2022). "CD14+ monocytes were isolated from whole blood, cultured, and treated with the GCF of periodontitis patients to observe if they differentiated into macrophages." (PMID 34203667, 2021). "To confirm the presence of macrophages, we also examined the expression of the macrophage markers CD14, CD68, CD86, and CD163 in gingival biopsies from periodontally healthy individuals and periodontitis patients." (PMID 33513808, 2021). "The presence of macrophage markers CD14, CD86, CD68, and CD163 was examined in gingival biopsies from healthy individuals and periodontitis patients." (PMID 33513808, 2021). "Changing in the extracellular levels of soluble CD14 might influence the responsiveness of hPDLSC to different pathogens and might have a potential effect on their immunomodulatory properties, which might play an important role in the pathogenesis of periodontitis." (PMID 27504628, 2016). "This study investigated the effects of T2DM and periodontitis on TLR4, CD14, MD-2 and MyD88 mRNA expression in surgically removed periodontal tissues." (PMID 26581717, 2015). "In this context, we have demonstrated in the current study that CD14-ablation protects against HFD-induced inflammation-triggered diabetes and periodontitis." (PMID 23133617, 2012). "Our study demonstrated that patients suffering from chronic periodontitis present more commonly with the 1654A/A genotype on the DEFB1 gene and the 159T/T genotype on the CD14 gene." (PMID 23046822, 2012). "It has been documented that the proportion of (CD14 + CD16+) non-classical monocytes in the blood are elevated in chronic periodontitis;A total of 20 chronic generalized periodontitis patients who were otherwise healthy, were recruited for this study." (PMID 38229101, 2024). "The CD14 + CD16+ non-classical subset of monocytes have also been found to be elevated in individuals with chronic periodontitis." (PMID 38229101, 2024). "In periodontitis, MANSC1 was negatively correlated and the other four hub crosstalk genes (FMNL1, PLAUR, RNASE6, and TCIRG1) were positively correlated with five hub IRRGs, namely, AQP9, C5AR1, CD14, CSF3R, and PLAUR." (PMID 36545026, 2022).
periodontitis (continued). "A higher proportion of PBMC cells related to wound healing (CD3+, CD3+ CD4+ CD8−, CD14+) were found in the PRF of control, periodontitis and neoplasia groups compared to the respective blood samples, which implies a positive outcome associated with clinical PRF usage in canine patients." (PMID 36261500, 2022). "SNPs in CD14, NF-κΒ, TLR2, and TLR4 are no risk modulators for preexisting CV events or severe periodontitis in CV patients." (PMID 34305452, 2021). "Our analyses revealed a significantly higher abundance of intermediate monocytes (CD14+CD16+) as well as non-classical monocytes (CD14+CD16++) in periodontitis-affected tissues." (PMID 32210958, 2020). "However, when the patients in Group 2 were combined with Group 3 (patients with both periodontitis and T2DM), the CD14 expression was significantly lower than that in Group 1 (p = 0.04)." (PMID 26581717, 2015). "Results showed that although CD14 expression in Group 2 (patients with periodontitis alone) is lower than that in Group 1 (patients without both periodontitis and T2DM), the difference is not statistically significant." (PMID 26581717, 2015). "CD14 expression was downregulated across patients with neither periodontitis nor T2DM, patients with periodontitis alone, and patients with both periodontitis and T2DM." (PMID 26581717, 2015). "The current study demonstrates that patients with moderate to severe chronic periodontitis present more commonly with the -1654 A/A genotype on the DEFB1 gene and the -159 T/T genotype on the CD14 gene, in parallel with increased serum levels of hBD-2 and soluble CD14." (PMID 23046822, 2012). "Therefore, the meta-analysis on the relationship between TLR-2 gene polymorphism and periodontitis susceptibility has not been reported alone, while the meta-analysis on TLR-4 and CD14 has been published; the conclusions are still inconsistent." (PMID 32831974, 2020). "In this study, allele and genotype frequency distributions of TLR4 A896G (rs4986790), TLR4 C1196T (rs4986791), CD14 C-260T (rs2569190), RANKL (rs2277438), and OPG C163T (rs3102735) polymorphisms were analyzed in a total of 203 patients with periodontitis and 213 subjects without the disease." (PMID 31281226, 2019). "CD14 expression was highest among four genes in patients without periodontitis and T2DM (Group 1)." (PMID 26581717, 2015). "CD14 mRNA expression was downregulated across patients with neither periodontitis nor T2DM, patients with periodontitis alone and patients with both diseases, suggesting that CD14 mRNA expression is associated with a favorable host response or subjected to a negative feedback regulation." (PMID 26581717, 2015). "CD14+ monocytes secrete a variety of cytokines, including TNF-α, IL-1β, IL-6, IL-8, CCL2, CCL3, and CCL5, compared to CD14− cells from GCF in patients with periodontitis, which suggests that CD14+ monocytes may be a source of CCL5 in GCF and gingival tissue in patients with periodontitis." (PMID 38139161, 2023). "To test our hypothesis, we collected periodontal tissues from patients with or without periodontitis and T2DM at the time of necessary surgeries and determined the mRNA expression of TLR4, CD14, MD-2 and MyD88 using quantitative real-time polymerase chain reaction (PCR)." (PMID 26581717, 2015). "Furthermore, we found that CD14 expression in Group 3 is significantly lower than that in Group 1 (p = 0.003), indicating that periodontal CD14 expression in patients with both periodontitis and T2DM is significantly lower than that in patients without periodontitis and T2DM." (PMID 26581717, 2015).
diabetes (48 papers, 2012 to 2026). "Hypertension and diabetes mellitus are potential effect modifiers of the association between cognition and CD14+CD16+ monocyte transmigration across the BBB." (PMID 39253970, 2024). "After an adjustment for the presence of diabetes mellitus, arterial hypertension and smoking, all parameters excepting hyperLp(a) and the percentage of intermediate CD14++CD16+ monocytes lost their significance as a risk factor for triple-vessel CAD." (PMID 34206012, 2021). "Many studies have assessed the implication of cluster of differentiation 14 (CD14) molecules and its single nucleotide polymorphism rs2569190A>G with different complex diseases, such as diabetes and cardiovascular diseases (CVDs)." (PMID 31671579, 2019). "Similar metabolic activation of CD14+ cells in obese individuals was associated with diabetes outcome." (PMID 29333574, 2018). "To examine the long-term influence of partial innate immune signaling disruption on glucose homeostasis, we analyzed knockout mice deficient in CD14 backcrossed into the diabetes-prone C57BL6 background at 6 or 12 months of age." (PMID 22253759, 2012). "Since chronic inflammation is an established risk factor for insulin resistance and type 2 diabetes, we hypothesized that CD14 inflammatory signaling would be associated with increased risk of diabetes onset." (PMID 38817635, 2024). "We showed that hypertension and diabetes may be effect modifiers on the association between CD14+CD16+ monocyte transmigration and cognition." (PMID 39253970, 2024). "Many studies have assessed the role of CD14, especially at the molecular level, and established a link between the gene product and its single nucleotide polymorphisms (SNPs) with different complex diseases such as diabetes and CVDs." (PMID 31671579, 2019). "Correlation anal is revealed significant associations between immune markers (CD14+, HLA-DR, IL-10, CD8+), clinical parameters (BMI, coronary heart disease, hypertension, diabetes), and behavioral factors (physical activity, smoking, alcohol)." (PMID 40218200, 2025). "Sending signaling of CD14 monocytes was increased in T2D and the outgoing interaction strength of CD14 monocytes was higher in T2D patients than in non-diabetes." (PMID 39072276, 2024). "One study found that patients with type 1 diabetes mellitus (T1D) have significantly greater numbers of MDSCs in their peripheral blood with M-MDSCs (CD14+ CD33+ HLA-DR−) being the most prevalent subset of MDSCs." (PMID 39290701, 2024). "T2D patients showed higher proportions of NK cells and CD16 monocytes, while B cells and CD14 monocytes were significantly more abundant in non-diabetes." (PMID 39072276, 2024). "Further analysis of CD14 monocytes by pseudobulk differential expression analysis, the expression of pro-inflammatory genes differentiated between non-diabetes and T2D patients and were highly expressed in T2D patients." (PMID 39072276, 2024). "CD99, CLU, CD14, and SAA2 have been reported to be associated with diabetes from human serum proteins." (PMID 33995275, 2021). "In patients with diabetes mellitus, the CD14 expression on monocytes is inversely correlated with HDL cholesterol levels." (PMID 33799511, 2021). "Comparing expression of CASK between CD14+ cells of rFSGS patients and those from patients with diabetes mellitus or transplant patients or healthy donors, we observed a higher expression in rFSGS CD14+ cells." (PMID 32477353, 2020). "The clinical importance of CD14 as a predictive marker of insulin resistance and type 2 diabetes mellitus among women with PE during pregnancy should be further examined in large multi-centre cohorts." (PMID 32066653, 2020). "In contrast, jumonji domain-containing protein D3 (JMJD3), an anti-inflammatory transcription factor for myeloid cells, was significantly under-expressed in diabetes CD14 monocytes (p < 0.05)." (PMID 32210958, 2020).
diabetes (continued). "Yan WJ, Sun P, Wei DD, Wang SX, Yang JJ, Li YH, Zhang C. T cell immunoglobulin and mucin domain‐containing molecule 3 on CD14+ monocytes serves as a novel biological marker for diabetes duration in type 2 diabetes mellitus." (PMID 30180306, 2018). "For example, circulating CD34(+) and CD14(+) PBMCs express and secret the antiomiR-126, and an alteration of angiomiR-126 expression in CD34(+) PBMCs in diabetes provides a novel pathway causing impaired proangiogenic effects." (PMID 24865854, 2014). "As some GPI-anchored proteins are released from cells by treatment with glimepiride, a sulphonylurea used for the treatment of diabetes, the effects of glimepiride upon CD14 expression and cytokine production from cultured macrophages were studied." (PMID 24952384, 2014). "Additionally, CPA patients diagnosed with COPD had a significantly reduced frequency of cDC1s and those with diabetes had a significant increase in the frequency of CD14+CD16- monocytes." (PMID 40503945, 2025). "For example, cluster of differentiation 14 (CD14), a monocyte differentiation antigen, has been reported to modulate inflammation-driven insulin resistance and has been identified as an inflammatory marker in women with diabetes and impaired glucose tolerance." (PMID 33995275, 2021). "Expression of HIF1a was significantly higher in the diabetes CD14 monocytes (p < 0.05)." (PMID 32210958, 2020). "Moreover, the increased sCD14 levels in NASH patients were highly correlated with increased hepatic CD14 expression and liver inflammation, even after adjusting for age, sex, presence of diabetes, dyslipidemia, hypertension, BMI, VFA, and SFA." (PMID 23762319, 2013). "Interestingly, our current study revealed that CD14 monocytes in T2D exhibited a significantly higher pro-inflammatory score and enriched pathways associated with MHC class II protein complex binding and RETN-CAP1 interaction compared to the non-diabetes." (PMID 39072276, 2024). "Similarly, CD14+DN cells from patients with diabetes produced significantly less IL-8 (P < 0.05 for comparison to NoDR; P < 0.001 for DR patients), while HGF and IL-3 secretion was only significantly less in the DR group (P < 0.001, and P < 0.01, respectively)." (PMID 38983045, 2023). "Moreover, modulation of adverse immune processes could be dampened via the observed shift of CD14+ cells into a pro-regenerative phenotype and the enhanced induction of regulatory T cells in selected autoimmune diseases, such as diabetes or arthritis." (PMID 31133024, 2019). "Eight studies investigated monocytes/macrophages in the liver under diabetes, using nine markers to identify monocytes/macrophages in mice (CD11b, Ly6C, F4/80, CD11c, CD206, and CD86) and humans (CD14, CD16, and CD68) at protein or RNA levels." (PMID 40362271, 2025). "In this study, T2D patients demonstrated a decreased proportion of CD14 monocytes and an increased proportion of intermediate and CD16 monocytes compared to non-diabetes." (PMID 39072276, 2024). "The percentage of these two subsets among classical CD14+ monocytes is reported to increase in various inflammatory diseases, including CAD and diabetes." (PMID 38553774, 2024). "Diabetes patients had a higher AIP (p = 0.005), as well as a significant increase in the levels of the CD14 (<0.001) and CD26 (0.033) proteins." (PMID 35846887, 2022). "Urinary excretion of CD14, HEXA, and LUM was significantly elevated in early diabetes as reported by Singh and colleagues, but was variable in the study by Suh and colleagues." (PMID 32453760, 2020). "(b) Correlation analysis of Tim‐3 expression on CD14+ monocytes cells and type 2 diabetes patients’ fasting plasma glucose (FPG), glycated hemoglobin (HbA1c), insulin, body mass index (BMI), age and diabetes duration." (PMID 30180306, 2018).
diabetes (continued). "Due to collection of circulating PBMCs only in a sub-set of the participants, there were not enough participants within the diabetes CTCA subgroup to analyze for gene expression of CD14 and TLR4 in circulating PBMCs." (PMID 39563343, 2024). "We have measured the expression of IDOL in CD14+ monocytes in subjects with and without type 2 diabetes and shown that IDOL expression in CD14+ monocytes was significantly reduced in individuals with diabetes compared with healthy nondiabetic control." (PMID 37094639, 2023). "In mice treated with empagliflozin, the diabetes-induced upregulation of Tgfβ1 and Cd14 was absent and there was a trend for reduced Fn1 expression compared to vehicle-treated db/db mice (P = 0.059)." (PMID 27226136, 2016). "Pre-treatment of RAW 264 cells with 5 μM glipizide, another sulphonylurea used to treat diabetes, did not affect the amounts of CD14 in cells (data not shown)." (PMID 24952384, 2014). "The aim of our study therefore was to provide quantitative data on CD14++CD16− and CD14+CD16+ monocyte subsets in juvenile-onset complication-free diabetes mellitus type 1 and to compare them with the corresponding values in the healthy age- and sex-matched control group." (PMID 25053869, 2014). "Additionally, comparison of the expression level of LAMA2, MLL4, PLXDC2, CD14, CLU, CD99 and SAA2 in sera of healthy volunteers and patients with stroke and pre-diabetes suggests that LAMA2, MLL4 and PLXDC2 have better specificity for (pre-)diabetes than CD14, CLU, CD99 and SAA2." (PMID 33995275, 2021). "Interestingly, metabolic activation as found in the ATM part of obese adipose tissue was also apparent in CD14+ cells isolated from visceral adipose tissue of obese humans with diabetes compared with obese non-diabetic individuals." (PMID 29333574, 2018). "Using established FACS protocols for the detection of EPCs and SMPCs we observed that the frequency of circulating CD34+ and CD34+KDR+ cells is reduced in patients with diabetes, whereas the levels of CD14+CD105+ SMPCs are not significantly changed by the presence of diabetes." (PMID 22648662, 2012). "In human studies, non-classical CD14+CD16++ and intermediate CD14++CD16+ hepatic macrophages were more prevalent in diabetes with NASH or cirrhosis than diabetes alone." (PMID 40362271, 2025). "A detailed role of CD14+CD16+ monocytes in hypertension and diabetes pathogenesis has not been characterized in PWH or in the general population." (PMID 39253970, 2024). "Moreover, sCD14 concentrations were significantly higher in subjects with diabetes with atherosclerotic plaques compared to subjects without diabetes and without atherosclerotic plaques, possibly reinforcing the notion that CD14 may be released under these settings." (PMID 37237950, 2023).